MELK (maternal embryonic leucine zipper kinase)
Diseases named in the same sentence as MELK in open-access papers (continued):
Sharing a sentence is not in itself a finding about the gene and the disease.
tumor (124 papers, 2006 to 2026). "This multi-omics-driven model elucidates MELK-mediated mechanisms and their interactions with the tumor microenvironment, providing novel strategies for risk stratification and targeted therapy." (PMID 40709174, 2025). "Overexpression of MELK has been documented in several malignancies and is often associated with tumor proliferation, invasion, and treatment resistance." (PMID 40564876, 2025). "The results showed that control HCC-LM3 cells caused more aggressive tumor lung metastasis than MELK knockdown HCC-LM3 cells." (PMID 38970074, 2024). "MELK inhibitor has been associated with enhanced radiosensitivity and suppressed tumor growth in animal models." (PMID 38167429, 2024). "Overall, the dysregulation of mitochondrial function associated with MELK in tumor cells induced mitochondrial damage and cell death." (PMID 37949877, 2023). "All patients displayed an association of OS with MELK, age, vascular invasion, and tumor status (with tumor or tumor-free), indicating that these were independent prognostic factors for OS." (PMID 35511171, 2022). "This showed that MELK levels were significantly linked to both tumor diameter (p = 0.029) and tumor-node-metastasis (TNM) stage (p = 0.032)." (PMID 35511171, 2022). "In the Wurmbach Liver dataset, higher MELK mRNA levels were associated with both tumor grade and vascular invasion." (PMID 35511171, 2022). "The results indicated that up-regulation of MELK by ncRNAs is linked to both tumor infiltration and poor outcome in HCC." (PMID 35511171, 2022). "First, we observed overexpression of MELK in BCa cell lines and tissues and found that it was associated with higher tumour stage and tumour grade, which was consistent with transcriptome analysis." (PMID 31821699, 2020). "The expression and association between STRAP and MELK were also attenuated by sanguinarine in the tumor tissues." (PMID 29783958, 2018). "In cohorts of patients with tumor types in which MELK levels have previously been associated with advanced disease, MELK expression was significantly correlated with each of the proliferation genes (median correlation = 0.82)." (PMID 29417930, 2018). "In the bivariate models, MELK was significantly associated with patient outcome in only 2 of 15 datasets, demonstrating that considering tumor cell proliferation ablated MELK’s clinical utility." (PMID 29417930, 2018). "MELK encoding maternal embryonic leucine zipper kinase appears to play a role in governing proliferation and conferring anti-apoptotic properties to tumor cells." (PMID 29212506, 2017). "The high MELK expression was associated with poor prognosis and advanced tumor stage (CIN3/CIS and invasive cancer)." (PMID 29312619, 2017). "When subgroups are customized with tumor grades, we found that higher MELK expression level was significantly associated with higher histological grades among all of the datasets." (PMID 28327601, 2017). "Although MELK-targeting therapy in PDX models markedly suppressed tumor growth, it also resulted in modest body weight loss (less than 20%)." (PMID 26701722, 2016). "Furthermore, the identification of MELK as a key driver gene and its association with the immunosuppressive tumor microenvironment highlight new avenues for targeted therapy in high-risk patients." (PMID 40709174, 2025). "All patients showed an association between OS and MELK, age, vascular invasion, and tumor status." (PMID 35511171, 2022). "MELK is highly expressed in various tumors and associated with tumor progression." (PMID 36353126, 2022). "In the multivariate analysis, DFS was associated with MELK (HR 2.251; 95% CI 1.274–3.977; p = 0.005), tumor stage (T1 and T2 vs. T3 and T4, HR 2.416; 95% CI 1.398–4.175; p = 0.002), tumor status (tumor-free vs. with tumor, HR 6.558; 95% CI 4.006–10.738; p < 0.001), and AFP (AFP ≤ 200 VS." (PMID 35511171, 2022). "It suggested that MELK expression was positively associated with tumor occurrence." (PMID 34671205, 2021).
tumor (continued). "Notably, it revealed that high MELK protein expression was also significantly associated with higher pathological tumor-nodule-metastasis stage, vascular invasion." (PMID 32047721, 2020). "It is not known whether EZH2 phosphorylation can be mediated by upstream MELK and whether the process underlying phosphorylation is indispensable for tumor progression." (PMID 31380279, 2019). "However, in one of the MELK-positive tumor models, all PDX mice showed obvious body weight loss, regardless treatment." (PMID 26701722, 2016). "In this review we aim to summarize the current understanding of MELK biology, including its functions in cell cycle regulation, apoptosis, oncogenic signaling pathways, and tumor stemness." (PMID 41594935, 2026). "It has been shown that higher MELK levels are often correlated with unfavorable prognosis, aggressive tumor manifestations, resistance to treatment, and stem-like tumor morphologies." (PMID 41594935, 2026). "In this study, we integrate clinical data analyses with preclinical models to examine the impact of MELK expression on survival, tumor-initiating properties, and metastatic potential." (PMID 40076867, 2025). "We constructed a Hepa1-6 tumor model to clarify further the role of FABP5 in regulating MELK-mediated RFA sensitivity in HCC." (PMID 39871325, 2025). "IHC staining further demonstrated that MELK expression was higher in tumor tissues than in normal adjacent tissues (NAT), confirming that MELK levels are elevated in tumor tissues." (PMID 40709174, 2025). "Nanoparticles with high affinity to tumor cells were applied as a new therapy to interfere with the expression of maternal embryonic leucine zipper kinase (MELK)." (PMID 39871325, 2025). "Our functional studies demonstrated that MELK knockdown potently inhibited tumor cell proliferation, migration and invasion in ccRCC cell lines." (PMID 40709174, 2025). "Previous studies in tumor cells have shown that MELK can phosphorylate downstream regulatory proteins such as EZH2 and ASK1, thereby altering the activity of major signaling pathways." (PMID 41278210, 2025). "Tumor growth volume and weight were significantly smaller in the MELK knockdown and RFA-treated groups than those in control group." (PMID 39871325, 2025). "Mechanically, MELK knockdown or RFA treatment inhibited tumor proliferation and migration but promoted apoptosis, the combination enlarged this effect." (PMID 39871325, 2025). "The high expression of MELK in HCC tumor tissue predicted a decrease in survival and an increase in recurrence rate." (PMID 39871325, 2025). "A protein involved is maternal embryonic leucine zipper kinase (MELK), which mediates various cascades of signal transduction, thus regulating the tumor microenvironment (TME)." (PMID 40277919, 2025). "LINC00461 acts as a molecular sponge for the tumor-suppressive microRNA miR-485-3p, maintaining expression of the cell cycle regulator maternal embryonic leucine zipper kinase (MELK) and promoting GBM proliferation." (PMID 40450300, 2025). "While the reductions in tumor volume and weight were greater in group combining MELK knockdown with RFA treatment, FABP5 overexpression prevented the enhanced effect of the combined treatment." (PMID 39871325, 2025). "The oncogene maternal embryonic leucine zipper kinase (MELK) functions as a suppressor of cuproptosis to contribute to tumorigenesis and tumor progression." (PMID 40341098, 2025). "Inhibiting tumor cell-intrinsic MELK favors the activation of M1 macrophage polarization, inhibiting M2 macrophage polarization and the stimulation of CD8+ T cell attraction." (PMID 40860678, 2025). "The tumor inhibition effect of FABP5 knockdown was found to be similar to that of MELK knockdown in the Hepa1-6 subcutaneous tumor bearing model." (PMID 39871325, 2025).
tumor (continued). "We then performed ELISA to detect the secretion level of CCL2 in serum from mouse xenograft models bearing MELK knockdown tumors or the corresponding control tumors, and a reduced concentration of CCL2 was detected in MELK knockdown tumor-bearing mice." (PMID 38970074, 2024). "Then, we further explored the role and underlying mechanism of immune microenvironment regulation in the combination of MELK knockdown with RT treatment, and we analyzed immune infiltration in tumor tissues." (PMID 38970074, 2024). "There is increased evidence for the hyperactivation of MELK in a broad range of human malignancies, where MELK plays a central role in tumorigenesis and is involved in tumor progression through multiple pathways." (PMID 38970074, 2024). "We constructed BALB/c nude mouse tumor xenograft models by subcutaneously injecting HCC-LM3 cells transfected with shSCR or shMELK and found that MELK inhibition significantly suppressed tumor growth, confirming the pro-oncogenic effect of MELK." (PMID 38970074, 2024). "DEP Domain Containing 1 (DEPDC1) and Maternal Embryonic Leucine Zipper Kinase (MELK) are directly associated with oncogenesis and tumor progression." (PMID 39596419, 2024). "In animal models, MELK inhibition has increased the survival of affected mice and inhibited tumor growth." (PMID 38167429, 2024). "Consistently, as indicated by macroscopic changes and pathological features, MELK knockdown substantially attenuated tumor occurrence and suppressed tumor growth." (PMID 38970074, 2024). "We need to conduct further experiments to verify the specific biological mechanisms of PYCR1 and MELK as well as the tumor-immune axis in ccRCC." (PMID 37340189, 2023). "Overexpression of MELK promoted tumor proliferation, migration, stemness, and Akt/mTOR signaling activity." (PMID 37949877, 2023). "Then, we demonstrated the overexpression of PYCR1 and MELK in ccRCC and verified this finding by analyzing tumor specimens, and overexpression of these genes indicates a poor prognosis for ccRCC patients." (PMID 37340189, 2023). "Although MELK expression is tightly regulated in normal cells, it is significantly upregulated in a variety of tumor tissues." (PMID 37340189, 2023). "Core genes (CEACAM1, CEP55, MELK) and were found to be involved in tumor, inflammation, necrosis, and proliferation." (PMID 37589542, 2023). "Recent studies have shown that MELK contributes to tumorigenesis and tumor progression through activation of the PI3K/mTOR cascade." (PMID 37949877, 2023). "Hematoxylin and eosin staining showed that control tissues contained approximately 95% tumor cells, whereas the number of nodules was lower in MELK KO tissues." (PMID 37377604, 2023). "The present results pronounce the importance of the Maternal embryonic leucine zipper kinase (MELK) gene as one of the most influential hub genes in both primary tumor cells and the P7731 cell line." (PMID 37231064, 2023). "More importantly, MELK KO and treatment with MELK-In-17 suppressed lung metastasis and tumor growth in animal models." (PMID 37377604, 2023). "More importantly, MELK inhibition with a novel selective MELK inhibitor suppressed tumor growth, and MELK KO suppressed lung metastasis in TNBC xenograft mouse models." (PMID 37377604, 2023). "The specimens were collected from 38 ccRCC patients, including tumor tissues or adjacent tumor tissues, and stained for MELK." (PMID 37340189, 2023). "Firstly, we began by comparing the expression of the DNMT1, DNMT3A, and DNMT3B methyltransferases in relation to MELK tumor expression, revealing that all three were up-regulated in the context of higher MELK expression." (PMID 35511171, 2022). "It is notable that the MELK gene is located within the pericentromeric region of chromosome 9 (9p13.2) that harbors several tumor-related genes." (PMID 35749404, 2022). "There was significantly increased nuclear and cytoplasmic MELK staining in advanced tumor compared with benign tissues." (PMID 35749404, 2022).
tumor (continued). "After adjustment for tumor purity, a significant positive correlation was observed between MELK and the expression of these immune checkpoint genes." (PMID 35511171, 2022). "In summary, our work suggested that ncRNA-mediated overexpression of ﻿MELK was correlated with poor prognosis, tumor immune infiltration, and immunotherapy efficacy of patients in HCC." (PMID 35693941, 2022). "Overexpression of MELK was found to correlate with early tumor recurrence and poor patient survival in HCC." (PMID 35511171, 2022). "Correlation heat map showed that tumor purity decreased as MELK expression increased, while the ESTIMATE score, immune score, and stromal score increased with the increase in MELK expression." (PMID 36353126, 2022). "In vivo experiments confirmed that knocking down MELK in HeLa cells significantly reduced tumor growth rate." (PMID 34671205, 2021). "Although previous studies provided evidence that MELK plays an important role in tumorigenesis, the precise role of MELK in tumor development has been challenged by more recent studies." (PMID 34550356, 2021). "Western blot assays also demonstrated compared to sh-NC group, MELK protein level was declined in BBOX1-AS1-depletion tumor tissues." (PMID 33931086, 2021). "qRT-PCR assay manifested that knockdown of BBOX1-AS1 led to a decrease of BBOX1-AS1 and MELK expression, while an enhancement of miR-27a-5p expression in tumor tissues." (PMID 33931086, 2021). "KLF5-induced BBOX1-AS1 exerts tumor-promotive roles in NSCLC via sponging miR-27a-5p to activate MELK/FAK signaling, providing the possibility of employing BBOX1-AS1 as a therapeutic target for NSCLC patients." (PMID 33931086, 2021). "As the time of MELK-8A treatment of tumor cells increased, the cell proliferation activity gradually decreased." (PMID 34671205, 2021). "Inhibition of MELK significantly increases the sensitivity of various tumor models to radiotherapy and chemotherapy." (PMID 33520717, 2020). "The number of tumor cells that migrated through the membrane of transwell chamber was significantly increased by MELK in both KYSE70 and EC109 cells." (PMID 32047721, 2020). "The continuous measurement of tumour growth activity and the weighing of dissected tumours revealed that MELK inhibition significantly suppressed BCa growth in vivo compared with what was observed in control group mice." (PMID 31821699, 2020). "High MELK protein expression was significantly related with tumor number, tumor size and recurrence." (PMID 32047721, 2020). "H&E staining indicated that the sh‐MELK group of tumour tissues contained fewer tumour cells than the tumours in the NC group mice, suggesting weaker tumour activity in the sh‐MELK group." (PMID 31821699, 2020). "More importantly, enforced expression of MELK also promoted tumor growth and metastasis in animal models." (PMID 32047721, 2020). "Consistently, the number of tumor cells invaded through Matrigel were decreased in MELK-depleted KYSE30 cells, compared to that of the control group with shNC transfection; A similar phenomenon was also observed in EC9706 cells." (PMID 32047721, 2020). "Consistently, the cohort study further proved that MELK expression in BCa tissues was up‐regulated at the mRNA level and was correlated with tumour progression." (PMID 31821699, 2020). "Nude mice models of subcutaneous tumor growth and lung metastasis were performed to examine the function of MELK in tumorigenecity and metastasis of ESCC cells." (PMID 32047721, 2020). "Both in vitro and in vivo studies indicated that MELK silencing with siRNA/shRNA or OTSSP167 treatment exhibited anti‐tumour effects through abrogating cell proliferation and migration." (PMID 31821699, 2020). "The tumor growth curve of EC109-MELK group was much higher than that of the EC109-Vector group, suggesting that MELK promoted the tumor growth of ESCC cells in vivo." (PMID 32047721, 2020).
tumor (continued). "Chi‐square testing showed that the MELK level was significantly correlated with gender, age, T stage, N stage, tumour grade and progression." (PMID 31821699, 2020). "More importantly, further analysis indicated that the expression levels of MELK mRNA were positively related to the tumour stage and tumour grade in BCa." (PMID 31821699, 2020). "Combined with the clinicopathological information, further analysis indicated that the expression levels of MELK mRNA were positively related to the tumour stage and tumour grade in BCa." (PMID 31821699, 2020). "These tumour biological functions were markedly enhanced in cells when MELK was overexpressed in them." (PMID 31821699, 2020). "More importantly, enhanced expression of MELK greatly accelerated tumor growth and lung metastasis of ESCC cells in vivo." (PMID 32047721, 2020). "The number of metastatic tumor nodules in the lungs was much smaller in MELK-downregulated group than that of the control group." (PMID 32047721, 2020). "Consistent with the experimental results of MELK silencing by siRNA or shRNA, OTSSP167, an inhibitor targeting MELK, displayed anti‐tumour activity against BCa cells both in vitro and in vivo." (PMID 31821699, 2020). "MELK is a cell cycle-dependent kinase localized at chromosome 9p 13.2, whose expression is increased in many tumor tissues and in mitotically blocked cells, indicating that MELK expression is controlled during cell proliferation." (PMID 31861475, 2019). "Although mounting evidence indicates elevated levels of MELK in many tumor types, the molecular mechanisms responsible for the unrestrained activity of MELK remain poorly defined, and reports dealing with its regulation are scanty." (PMID 31861475, 2019). "Decreased tumor volume and Ki-67 index were achieved after the OTSSP167 and ACHP treatment (p < 0.001), which suggested that MELK/EZH2/NF-κB axis was essential to tumor proliferation." (PMID 31380279, 2019). "The current study revealed that the tumor-specific MELK activity is essential for the EZH2/NF-κB interaction via enhancing the methyltransferase activity and promotes the GSCs proliferation and maintains the stemness." (PMID 31380279, 2019). "MELK was revealed to be commonly up-regulated in differing types of solid tumor, with crucial roles in formation and maintenance of tumor stem cells." (PMID 31412643, 2019). "In the present investigation, we focused on the role in cholangiocarcinogenesis of MELK, a gene frequently activated in a variety of tumor types." (PMID 31861475, 2019). "Intriguingly, the survival of NSCs isn't affected by MELK knockdown, suggesting that MELK activation is specific to tumor." (PMID 31380279, 2019). "After injection into nude mice, these cell populations grew more rapidly than any clonal cell line, and the MELK-depleted cells exhibited equivalent or superior tumor growth compared to the control populations." (PMID 29417930, 2018). "While MELK is up-regulated in diverse tumor types, it is also expressed in several normal cell lineages, including embryonic cells, hematopoietic cells, and neural progenitor cells." (PMID 28337968, 2017). "In conclusion, our findings provide further evidence of mode of mechanism that OTS167 suppresses tumor growth by impairment of the MELK signaling pathway." (PMID 26918358, 2016). "Our data should further shed light on the mechanism of action how OTS167 suppresses tumor growth through the inhibition of the MELK signaling pathway and suggest the possibility of biomarkers for the assessment of clinical efficacy." (PMID 26918358, 2016). "MELK also localized to tumor cells and in particular the basal regions of crypts of normal gastrointestinal epithelium—the stem cell location in normal colonic tissue." (PMID 25852826, 2015). "As a result, we have a better understanding of some basic mechanisms, functions, and signaling pathways involving MELK, including interactions that link it with tumor progression." (PMID 25852826, 2015).